GAS6 (growth arrest specific 6)
Diseases named in the same sentence as GAS6 in open-access papers (continued):
Sharing a sentence is not in itself a finding about the gene and the disease.
subarachnoid hemorrhage (1 paper, 2023). A serious neurological disorder characterized by intracranial hemorrhage into the subarachnoid space. "Oligodendrocyte generation and increased myelin production for repair have been shown to be stimulated by the signaling of Gas6, a VKDP, in a mouse model, and Gas6 appeared to reduce damage following subarachnoid hemorrhage through its role in cytokine signaling." (PMID 37232626, 2023).
uremia (1 paper, 2016). A clinical syndrome associated with the retention of renal waste products or uremic toxins in the blood. "However, here we failed to observe increased apoptosis in Gas6-/- mice in vivo and in vitro when compared to WT mice and we thus cannot confirm a role of Gas6 in an anti-apoptotic pathway in our uremia and calcification models." (PMID 27230889, 2016).
varices (1 paper, 2019). "A plasma Gas6 value < 45 ng/ml, detected in 34/160 (21%) patients, was 94% sensitive (but only 23% specific) in identifying patients without large varices; one of these patients (different from the subject missed by Baveno VI criteria) had large varices at upper gastrointestinal endoscopy." (PMID 31583026, 2019).
tumor (308 papers, 2008 to 2026). "One of its primary ligands, GAS6, is abundantly secreted by tumor-associated macrophages (TAMs), endothelial cells, and fibroblasts within the TME." (PMID 41011010, 2025). "The Gas6/AXL signaling pathway is closely related to the malignant behavior of tumor cells and can cause immunosuppression." (PMID 40538442, 2025). "GAS6 was expressed in tumour-associated-like population that promoted the expression of COLl1A1 and TGFB1 in human endometrial stromal cells." (PMID 40943271, 2025). "The most abundant lesion-resident population was LRM4 which was characterized by expression of Ccl8, Mrc1, Gas6, Marks, Cbr, and Folr2, a signature shared with many tumor-associated macrophages (TAM) (19, –21)." (PMID 39255000, 2024). "The copy number of CAR-T-cell DNA in peripheral blood was associated with tumor clearance, and copy numbers remained high for at least 42 days in the GAS6-CAR group compared to Mock controls." (PMID 37475048, 2023). "Research has indicated the role of the multifunctional protein Gas6, chiefly produced by tumor-associated macrophages (TAMs) and cancer-associated fibroblasts (CAFs), in propelling PDA metastasis." (PMID 37760801, 2023). "AXL is a member of the TYRO3, AXL, and MERTK (TAM) family of receptor tyrosine kinases (RTKs) that can be activated by the ligand Gas6, which is closely associated with tumor progression." (PMID 36105100, 2022). "In the TME, CAFs express Gas6 and the Gas6/Axl signaling pathway has been implicated in the promotion of tumor cell proliferation, survival, migration, invasion, angiogenesis, and immune evasion." (PMID 35523772, 2022). "Overexpression of tumor-associated growth arrest-specific protein 6 (Gas6) is found in many tumor entities." (PMID 35760058, 2022). "Gas6 and TAM play an important role in prognosis in different tumor types since higher expression of Gas6 is associated with poorer survival." (PMID 35760058, 2022). "AXL receptor tyrosine kinase and its ligand growth arrest-specific 6 (Gas6) have been implicated in tumor growth and proliferation of NSCLC." (PMID 36547898, 2022). "In VHL-deficient and hypoxic ccRCC tumor cells, protein kinase growth arrest-specific 6 (GAS6)/AXL is activated by HIF1A and HIF2A." (PMID 35659268, 2022). "Fibroblasts, tumor-associated macrophages, and endothelial cells are among the primary sources of GAS6 within the TME." (PMID 35572601, 2022). "The Gas6/Axl signaling pathway has been reported to be associated with tumor metastasis, invasion, and drug resistance." (PMID 36059952, 2022). "Current understanding is that tumor-associated macrophages are the primary source of Gas6 within the TME." (PMID 35127700, 2021). "Within TME, GAS6 is broadly available; it is secreted by some tumour cells, cancer-associated fibroblasts (CAFs), dendritic cells, and tumour associated macrophages." (PMID 34638349, 2021). "In the tumor microenvironment, cancer-associated fibroblasts (CAFs) and CD45+-expressing tumor-infiltrating leukocytes (TILs) also express Gas6." (PMID 32660000, 2020). "In vivo, the loss of Gas6 in FAKKO pericytes also reduced tumour size and angiogenesis in mice co-injected with FAK-null;Gas6KO and B16F0 tumour cells compared with mice co-injected with FAK-null;Cas9 pericytes and B16 tumour cells." (PMID 32499572, 2020). "Although the mechanisms underlying Gas6 upregulation in TILs is not fully understood, in vitro studies demonstrate that tumor cells or tumor cell conditioned media induce Gas6 expression and secretion in macrophages." (PMID 32660000, 2020). "The Gas6/Axl signaling pathway has been implicated in the promotion of tumor cell proliferation, survival, migration, invasion, angiogenesis, and immune evasion." (PMID 32660000, 2020). "Recently, Gas6 has been reported to be a crucial molecule implicated in tumor cell proliferation, anti-apoptosis, invasion and resistance to anticancer drugs." (PMID 32298237, 2020).
tumor (continued). "Together suggest S100A4 re-activate GemOE cells to secrete CCL2 that attracts macrophages and polarizes them into Gas6-secreting M2-tumor-associated macrophages (M2-TAMs42, 47, 48)." (PMID 31844158, 2019). "Another molecule associated to the composition of tumor microenvironment effects is the growth arrest specific 6 (Gas6), since it interacts with TAM receptors Mer, with the downstream effect of PI3K, ERK, and NK-kB pathway activation." (PMID 31998254, 2019). "Following radiation therapy in a colorectal cancer mouse model, MerTK, Protein S and Gas6 are upregulated in tumor associated macrophages." (PMID 31088471, 2019). "The tumor of this patient carried also an amplification of GAS6, whose elevated expression has been previously associated with a favorable prognosis in CRC." (PMID 31226844, 2019). "Within the tumor, CCL2 polarizes M0-macrophages into Gas6-secreting M2-tumor-associated macrophages (M2-TAMs)." (PMID 31844158, 2019). "The Gas6/AXL signalling pathway is associated with tumour cell growth, metastasis, invasion, epithelial-mesenchymal transition (EMT), angiogenesis, drug resistance, immune regulation and stem cell maintenance." (PMID 31684958, 2019). "Tumor-associated macrophages are stimulated to increase their Gas6 expression in the TME in comparison to resident tissue macrophages, which implicates a positive feedback loop in Gas6/Axl signaling." (PMID 30567378, 2018). "In contrast, tissue-resident macrophages isolated from lungs or from the peritoneum expressed much lower levels of Gas6 than tumour-associated macrophages." (PMID 29386018, 2018). "Further analysis revealed that tumour-associated macrophages are the primary source of Gas6 within the tumour microenvironment." (PMID 29386018, 2018). "The tumors in Gas6-deficient EL4-Axl-tumor bearing mice were much larger in volume and size than those of control rabbit Ig-injected EL4-Axl-tumor bearing mice." (PMID 28423548, 2017). "The expression of AXL was positively associated with GAS6 expression (P < 0.001), and tumor differentiation (P = 0.014) in advanced NSCLC with metastases." (PMID 28551766, 2017). "In support of a tumorigenic role of Gas6 in ectopic and orthotopic syngeneic mouse tumor models, recent studies showed that both growth of tumors and subsequent metastatic dispersal was abrogated in a Gas6 deficient mice (Gas6−/−) compared to wild-type mice." (PMID 27916840, 2016). "AXL and GAS6 were markedly present in less differentiated tumour specimens and only GAS6 was associated with lymph nodes status and consequently with tumour stage, showing a higher expression in more advanced disease." (PMID 25966280, 2015). "The results demonstrated that high serum Gas6 level was significantly associated with tumor nodal metastases." (PMID 26207647, 2015). "In oral squamous cell carcinoma (OSCC) cells, expression of Axl is increased during coculture with tumor-associated macrophages having abundant levels of Gas6." (PMID 25344858, 2014). "Statistically significant associations were found between Axl IHC score and tumor differentiation, p-stage, maximum tumor size, LN metastatic status, and serum tumor marker levels, as well as between Gas6 IHC score and LN metastatic status." (PMID 23242819, 2013). "High tumour expression of GAS6 (WA > 2) was associated with significantly shorter disease-free survival (P = 0.0004)." (PMID 23878800, 2013). "Calculation of the integrated score for an individual risk (ISIR), considering tumour size (T), lymph node status (N), metastasis (M), Gas6 and CD68 identified 82% of patients as having a clear risk status." (PMID 21794149, 2011). "For example, a recent article associated expression of GAS6 with indicators of good prognosis such as progesterone receptor positivity, small tumor size, low grade, and young patient age." (PMID 19995430, 2009).
tumor (continued). "Larger tumours (average size=38 mm) were associated with low Gas6 levels and smaller tumours (average size=22 mm) were associated with high Gas6 levels." (PMID 18283315, 2008). "High GAS6 levels were also substantially associated with tumor stage and grade." (PMID 39774471, 2025). "The GAS6/Axl pathway is implicated in resistance to tumor therapy." (PMID 40940956, 2025). "In addition, AXL and GAS6 are both described to drive tumor-associated macrophage polarization towards an immunosuppressive, pro-tumoral, M2-like phenotype via the AXL/PI3K/AKT/NFκB pathway." (PMID 39367387, 2024). "Increased CXCL1 expression also recruits neutrophils to the metastasis site; these cells secrete growth arrest specific 6 (Gas6), a secretory factor activating the Axl receptor tyrosine kinase that causes tumor cell proliferation and thus the regrowth of the metastatic site following chemotherapy." (PMID 37408240, 2023). "At 2-month of age, this may be related to the GAS6-tumor-associated macrophage (TAM) promoting myelination and glial cell development in the CNS." (PMID 37577391, 2023). "Therefore, it is expected that GAS6-CAR-T cells probably offer better clinical outcomes by targeting both tumor cells and tumor-associated macrophages." (PMID 37475048, 2023). "In the tumor stromal microenvironment, cancer-associated fibroblasts play an important role, and Gas6 could promote non-small cell lung cancer." (PMID 35053080, 2022). "In addition to GAS6, it is shown that tumor-associated microglia produce protein S which subsequently interacts with and activates AXL in mesenchymal GSCs and promotes growth of GBM cells, and inhibition of AXL suppresses the promoted growth of GBM cells." (PMID 34831142, 2021). "In addition, Gas6 has been implicated in the promotion of tumour cell proliferation, survival, migration, invasion, angiogenesis, and immune evasion, which it accomplishes via Axl signalling." (PMID 34717544, 2021). "GAS6 is usually thought to be related to cell proliferation, chemotaxis and survival, and stronger expression in BOTs implies associated epithelial-mesenchymal transition in the tumor microenvironment." (PMID 33921111, 2021). "AXL receptor tyrosine kinase, together with its ligand, growth-arrest-specific protein 6 (Gas6), is a new therapeutic target overexpressed in various cancers and significantly associated with tumor proliferation, metastasis, EMT, and acquisition of CSC characteristics." (PMID 32754598, 2020). "Furthermore, we confirmed an increase in stromal Gas6 expression during chemotherapy using clinical samples and showed that tumor Axl and stromal Gas6 expression are associated with poor prognosis." (PMID 28878389, 2017). "GAS6 overexpression was associated with nodes involvement and tumour stage." (PMID 25966280, 2015). "Gas6/Axl signaling activation could increase expression of mesenchymal markers when OSCC cells are co-cultured with tumor-associated macrophages." (PMID 26207647, 2015). "Axl, and its γ-carboxylated ligand, Gas6, are associated with drug-resistant tumor relapse." (PMID 26438693, 2015). "Gas6-positive tumours were associated with pushing margins on histological assessment." (PMID 18283315, 2008). "There was a significant inverse association between tumour size and Gas6 expression." (PMID 18283315, 2008). "Gas6 has displayed mitogenic activity in cell lines; however, in our cohort, Gas6 was associated with favourable prognostic markers including smaller tumour size (P=0.02), decreased levels of lymph node metastases (P=0.0002) and lower nuclear morphology (P=0.03)." (PMID 18283315, 2008). "Furthermore Gas6 may also be expressed in tumor-associated cells like macrophages, which we have previously shown in animal models." (PMID 27486820, 2016). "Increasing studies have emphasized the important roles of GAS6/AXL in tumor progression and TME reprogramming in multiple malignancies including NSCLC 58, making it an emerging therapeutic target." (PMID 41356185, 2026).
tumor (continued). "Blockade of either AXL or GAS6 enhances NK cell activation, reduces metastasis, and promotes tumour control in breast cancer, melanoma, and pancreatic cancer models." (PMID 40948757, 2025). "In tumor tissues, GAS6‐AXL‐mediated communication was more complex, involving myeloid cells, fibroblasts, endothelial cells, and occasionally thyrocytes." (PMID 40433916, 2025). "Immunohistochemical (IHC) analysis of tumor tissues confirmed that GAS6 + macrophage co-culture and GAS6 treatment promoted EMT (increased N-cadherin and decreased E-cadherin), which was attenuated by TYRO3 inhibition." (PMID 41034991, 2025). "In our study, GAS6 was significantly overexpressed in CAFs compared to NFs, suggesting a tumor-promoting role in the TME." (PMID 40940956, 2025). "GAS6 secreted by TANs and CAFs promotes tumour regrowth and invasion by activating TAM receptors expressed on cancer cells." (PMID 40044635, 2025). "We identifies WNT-activated tumor-initiating cells evading immune attacks by interacting with macrophages through the GAS6/AXL/MERTK pathway, suggesting new targets for cancer therapy." (PMID 39774471, 2025). "In leukaemia, AXL is induced by tumour-derived GAS6, which also acts on NK cells to reduce NKG2D expression and impair cytotoxicity." (PMID 40948757, 2025). "In pancreatic cancer, CAR-T cells with the extracellular domain of Gas6 have been seen to be highly effective in killing TAM-positive tumor cells in vitro and in mouse xenograft models." (PMID 40069722, 2025). "GAS6 antibody–treated mice exhibited delayed tumor burden and improved survival (median of 66 days) compared with controls (median of 45 days)." (PMID 39774471, 2025). "After 24 h of co-culture, tumor cell proliferation was significantly enhanced in the GAS6 + macrophage co-culture and GAS6 treatment groups compared to the PBS and GAS6- macrophage co-culture groups, while TYRO3 inhibition suppressed this effect." (PMID 41034991, 2025). "Gas6 allows for the localization of the therapeutic to the tumor site, using PS as a homing beacon, and the subsequent delivery of the proteins to the TME." (PMID 40069722, 2025). "Its activation through ligands such as Gas6 triggers multiple oncogenic pathways, contributing to immune evasion and tumor aggressiveness." (PMID 41011010, 2025). "Elevated Gas6 levels promote tumor progression, invasive activity, and angiogenesis, contributing to poorer prognosis." (PMID 41164270, 2025). "These cells express GAS6 stimulating AXL-dependent efferocytosis by tumour macrophages, M2 polarisation, immunosuppression and angiogenesis." (PMID 40044635, 2025). "In TNBC, the GAS6-AXL signaling within cancer cells seem to foster cell survival, whereas in HER2BC, elevated GAS6 expression triggers pro-tumor AXL signaling." (PMID 41219968, 2025). "Both human ICC scRNA-Seq and TCGA-CHOL data revealed higher GAS6 expression in tumor cells, with positive correlations to WNT signaling genes." (PMID 39774471, 2025). "The GAS6–Axl axis enhances tumor cell survival and invasion while fostering an immunosuppressive milieu." (PMID 41011010, 2025). "To investigate TIC-derived GAS6 suppression of tumor immunity via AXL/MERTK on Reg-TAMs, we used Krt19-DreER Axin2-creER R26-Ai66 mice for AKT/YAP/SB hydrodynamic injection and sorted Reg-TAMs and epithelial cell adhesion molecule+/Tom+ (EpCAM+Tom+) TICs." (PMID 39774471, 2025). "This suggests that CAF-derived GREM1 and GAS6 primarily contribute to skewing macrophages toward an M2 phenotype within the tumor microenvironment (TME)." (PMID 40940956, 2025). "For example, ADAM12 promotes efferocytosis and polarizes macrophages toward an immunosuppressive M2 phenotype in a tumor microenvironment via an AXL-dependent mechanism involving Gas6 secretion." (PMID 41181101, 2025). "Gas6, a vitamin-K-dependent (VKD) protein, has been shown to be highly expressed in human tumor tissues, and high levels of Gas6 expression are associated with poorer prognosis." (PMID 39451556, 2024).